LINC00662 (long independently transcribed non-coding RNA 662)
Gene: Long non-coding RNA gene on chromosome 19 (27,681,072 to 27,794,005, reverse strand). Ensembl gene ENSG00000261824.
Diseases named in the same sentence as LINC00662 in open-access papers:
LINC00662 is named in the same sentence as 23 diseases in open-access papers, as found by Europe PMC text mining. Sharing a sentence is not in itself a finding about the gene and the disease. The quoted sentences say what the papers report.
lung carcinoma (11 papers, 2020 to 2024). "Linc00662 exerts its oncogenic functions by directly interacting with Lin28, a potential diagnostic and therapeutic target for patients with lung cancer." (PMID 33425890, 2020). "Besides, LINC00662, facilitating the metastasis of lung cancer cells through interaction with LIN28, is in association with the unfavorable prognosis of lung cancer patients." (PMID 35037833, 2022). "Interestingly, LINC00662 has been found to have a potential diagnostic value for patients with lung cancer, chordoma, colorectal cancer, gastric cancer, and acute myelocytic leukemia." (PMID 34354995, 2021). "LINC00662 is highly expressed and promotes malignant progression in several types of cancer, including gastric cancer, lung cancer, and oral squamous cell carcinoma." (PMID 36334221, 2023). "Another study on lung cancer highlighted that the expression of LINC00662 promotes cell invasion and contributes to cancer stem cell-like phenotypes in lung cancer cells." (PMID 35158906, 2022). "Consistently, LINC00662 has been shown to be overexpressed in many different tumors, including lung cancer, breast cancer, cervical cancer, prostate cancer, chordoma, glioma, gastric cancer, and hepatocellular carcinoma." (PMID 34354995, 2021). "LINC00662 regulates lung cancer cell proliferation, migration and cell apoptosis in vitro." (PMID 35371316, 2022). "Besides, LINC00662 boosts cell invasion and cancer stem cell-like phenotypes in lung cancer." (PMID 32549791, 2020). "This study selected human lung cancer cell lines A549 and SPCA1 to determine the biological role of LINC00662." (PMID 35371316, 2022). "For example, LINC00662 facilitates cell migration, invasion, and stemness maintenance via interacting with LIN28 in lung cancer." (PMID 34621314, 2021). "However, the cause for LINC00662 activation and its biological mechanism in lung cancer tumorigenesis, especially, the global genes mediated by LINC00662 has not been established." (PMID 35371316, 2022).
hepatocellular carcinoma (10 papers, 2020 to 2025). A malignant tumor that arises from hepatocytes. "Interestingly, the association between the expression of LINC00662 and rs11083486 was also observed in patients with bladder carcinoma, whereas rs5770650 was found to be associated with C22orf34 expression in hepatocellular carcinoma." (PMID 35158906, 2022). "It has been reported that LINC00662 is mainly distributed in the cytoplasm of hepatocellular carcinoma cells." (PMID 35551606, 2022). "LINC00662 has been shown to be oncogenic in various cancers, including colorectal cancer, hepatocellular carcinoma, oral squamous cancer, and prostate cancer." (PMID 36202872, 2022). "LINC00662 is identified as a tumor-promoting marker because of its involvement in patient’s prognosis in hepatocellular carcinoma (HCC)." (PMID 34900986, 2021). "Linc00662 promotes hepatocellular carcinoma (HCC) progression and M2 macrophage polarization by upregulating WNT3A expression and secretion through competitive endogenous RNA (ceRNA) mechanism." (PMID 35071016, 2021). "Linc00662 facilitates hepatocellular carcinoma advancement by regulating a genomic methylation." (PMID 40764609, 2025). "Previous studies state that LINC00662 promotes M2 polarization in hepatocellular carcinoma." (PMID 36334221, 2023). "Furthermore, overexpression of LINC00662 has also been observed in other types of tumors, including breast, cervical, and prostate cancers and chordoma, glioma, and hepatocellular carcinoma." (PMID 35158906, 2022). "Upregulation of LINC00662 has been found in hepatocellular carcinoma and acute myeloid leukemia." (PMID 32633082, 2020). "Previous reports showed that LINC00662 could promote M2 macrophage polarization in hepatocellular carcinoma, thus we further explored whether PITX1/LINC00662 could mediate macrophage polarization to affect OS malignancy." (PMID 36334221, 2023).
oral squamous cell carcinoma (8 papers, 2020 to 2024). "LINC00662 was also found to accelerate prostate cancer, oral squamous cell carcinoma, colorectal cancer progression." (PMID 35551606, 2022). "For instance, knockdown of LINC00662 suppresses cell growth, migration, and invasion by mediating the epithelial-mesenchymal transition pathway in colorectal cancer and oral squamous cell carcinoma." (PMID 35123530, 2022). "Inhibition of LINC00662 reduces cell proliferative, migratory, and invasive abilities of in oral squamous cell carcinoma." (PMID 34621314, 2021). "Functionally, LINC00662 functioned as an miRNA sponge to promote the prostate cancer tumorigenesis through targeting miR‐34a,22 and LINC00662 was also found to promote proliferation and migration in oral squamous cell carcinoma." (PMID 32633082, 2020).
glioma (7 papers, 2020 to 2023). A benign or malignant brain and spinal cord tumor that arises from glial cells (astrocytes, oligodendrocytes, ependymal cells). "Herein, nine ferroptosis-related lncRNAs (AC062021.1, FAM66C, MIR497HG, TMEM72-AS1, AC010729.2, FAM225B, HOXA-AS2, LINC00662, and LINC00665) were identified to construct a risk model in patients with glioma." (PMID 35174152, 2022). "LINC00662 acts as an oncogene, promoting the development of glioma by blocking the miR-340-5p/STAT3 axis." (PMID 37305396, 2021). "Taken together, these studies suggest that LINC00662 serves as an oncogene in both glioma and chordoma and should be considered as a potential biomarker for treating these two tumor types that originate in the nervous system." (PMID 34354995, 2021). "RIP analysis revealed LINC00662, and miR-107 co-immunoprecipitate in Ago2 complex, and RT-qPCR analysis revealed that depletion of LINC00662 enhances miR-107 levels in glioma cells." (PMID 32913464, 2020). "Here, we examined the role of LINC00662 in glioma and found that it promotes glioma deterioration by regulating the LINC00662/miR-107/HMGB1 axis, suggesting its potential as a novel therapeutic target against glioma." (PMID 32913464, 2020). "We then explored LINC00662 expression in glioma by analyzing data from TCGA (The Cancer Genome Atlas) database and found that the expression of LINC00662 is dramatically elevated in glioma tissues." (PMID 32913464, 2020). "With the assistance of bioinformatic prediction tools, as well as ChIP and luciferase reporter assays, STAT3 was identified as a transcription factor responsible for LINC00662 up-regulation in OS cells by binding to the LINC00662 promoter region, consistent with a previous report in glioma." (PMID 36334221, 2023). "Moreover, they also confirmed that knocking down LINC00662 expression in an in vivo nude-mouse model inhibited glioma growth." (PMID 34354995, 2021). "What is more, LINC00662 is also closely related to gastric cancer, glioma, chordoma, and so on." (PMID 34659345, 2021). "In conclusion, our results indicate that LINC00662 acts as an oncogene in glioma by modulating the miR-107/HMGB1 axis, suggesting that LINC00662 could be a novel therapeutic target for glioma treatment." (PMID 32913464, 2020). "Results revealed that LINC00662 is mainly located in the cytoplasm, suggesting that LINC00662 might act as a miRNA sponge in glioma." (PMID 32913464, 2020). "Compared with the primary glioma group, the expression of AC062021.1, FAM225B, LINC00662, LINC00665, and TMEM72-AS1 was significantly different in the recurrent glioma group of the training CGGA693 cohort." (PMID 35174152, 2022). "Here, we show that LINC00662 directly interacts with miR-107 in the Ago2 complex and presented negative correlation in glioma tissues." (PMID 32913464, 2020).
gastric cancer (6 papers, 2020 to 2024). A primary or metastatic malignant neoplasm involving the stomach. "Bioinformatics analysis in gastric cancer suggested that LINC00662 overexpression is tightly related to poor patients’ prognosis." (PMID 35158906, 2022).
prostate carcinoma (6 papers, 2020 to 2022). A carcinoma that arises from epithelial cells of the prostate gland. "For example, silencing of LINC00662 represses cell migration, invasion, and proliferation by regulating miR-34a in prostate cancer." (PMID 35123530, 2022).
colorectal cancer (5 papers, 2021 to 2022). A primary or metastatic malignant neoplasm that affects the colon or rectum. "Consistently, LINC00662 high expression has been examined in cancer tissues of patients with colorectal cancer, indicating a positive correlation with tumor T stage." (PMID 35433661, 2022). "LINC00662 mediates the malignant phenotypes of colorectal cancer cells by the miR-145/c-myc axis." (PMID 34621314, 2021).
acute myeloid leukemia (4 papers, 2020 to 2021). Acute myeloid leukemia (AML) is a group of neoplasms arising from precursor cells committed to the myeloid cell-line differentiation. "LINC00662 acts as an oncogene in different human cancers such as acute myeloid leukemia (AML), GC, PC, LC, and HCC." (PMID 33522932, 2021).
breast carcinoma (4 papers, 2021 to 2024). "Moreover, many studies have reported that Linc00662 enhances cell stemness in breast cancer/osteosarcoma by sponging miR-144-3p/miR-16-5p22, 35, and that lncRNA CERS6-AS1 acts as an oncogene that facilitates xenograft tumor growth by binding to miR-15b-5p29." (PMID 38911389, 2024). "Finally, LINC00662 directly interacts with miR-186-5p to regulate cell viability and apoptosis in breast cancer." (PMID 36202872, 2022). "Consistent with previous study, we have found higher LINC00662 expression in breast cancer tissues than in non-diseased breast tissues." (PMID 36202872, 2022).
chordoma (4 papers, 2021 to 2022). Chordomas are rare malignant tumors arising from embryonic remnants of the notochord in axial skeleton. "Both LINC00662 and RNF144B have been shown to be aberrantly upregulated in chordoma tissues, and the knockdown of either LINC00662 or RNF144B impeded chordoma cell proliferation, colony formation, invasiveness, migration, EMT, and glycolysis." (PMID 34354995, 2021). "For instance, LINC00662 can facilitate chordoma development by activating RNF144B." (PMID 34721048, 2021). "Both LINC00662 and RNF144B expressions have been shown to be aberrantly upregulated in chordoma tissues, and their knockdowns resulted in the attenuation of chordoma cell proliferation, colony formation, invasiveness, migration, EMT, and glycolysis." (PMID 34354995, 2021).
cervical cancer (3 papers, 2021 to 2024). A primary or metastatic malignant neoplasm involving the cervix. "Linc00662 upregulation can affect the proliferation, invasion, and apoptosis of cervical cancer cells." (PMID 38911389, 2024). "The expression of LINC00662 was shown to be significantly upregulated in cervical cancer tissues and cells, and the high expression of LINC00662 resulted in reduced overall survival and relapse-free survival, and was associated with FIGO stage and lymph node metastasis." (PMID 35692795, 2022).
colon cancer (3 papers, 2020 to 2022). "For example, overexpression of LINC00662 increases colon cancer cell migration and invasion, whereas upregulation of LNC01082 inhibits SW480 and SW620 cell migration and invasion." (PMID 35502613, 2022). "LINC00662 overexpression promoted cell proliferation, invasion and migration, and inhibited cell apoptosis in colon cancer." (PMID 31900207, 2020). "LINC00662 overexpression promoted the occurrence and development of colon cancer by competitively binding with miR-340-5p to regulate CLDN8/IL22 co-expression and activating ERK signaling pathway." (PMID 31900207, 2020). "LINC00662 signally anabatic in colon cancer cell lines including HCT116, HCT8, HCT29, LOVO, SW480, CT26 and LS174T cells." (PMID 31900207, 2020). "In this study, high expression of LINC00662 was detected in colon cancer tissues and cell lines, and the survival rate of colon cancer patients with high expression of LINC00662 was lower than that of patients with low expression of LINC00662." (PMID 31900207, 2020). "This suggests that LINC00662 may play a role in the occurrence and development of colon cancer." (PMID 31900207, 2020). "Combined with the previous results, the effects of LINC00662 overexpression and CLDN8 overexpression on the biological function of colon cancer cells were consistent." (PMID 31900207, 2020).
esophageal squamous cell carcinoma (3 papers, 2020 to 2024). Esophageal squamous cell carcinoma (ESCC) is a type of esophageal carcinoma (EC) that can affect any part of the esophagus, but is usually located in the upper or middle third. "Given that, our study investigated the role of LINC00662 from esophageal squamous cell carcinoma (ESCC) cells-derived extracellular vehicles (EVs) in angiogenesis through microRNA (miR)-195-5p/vascular endothelial growth factor A (VEGFA) axis." (PMID 35433661, 2022).
gallbladder cancer (3 papers, 2024 to 2025). "For example, LINC00662, which is highly expressed in cancer patients, such as breast, colon, and prostate, is notably overexpressed in gallbladder cancer, and their elevated levels are significantly associated with larger tumor size and lymph node metastasis." (PMID 40141179, 2025). "Here, we show that LINC00662 is associated with larger tumor size and lymph node metastasis in patients with gallbladder cancer." (PMID 38928444, 2024). "In addition, LINC00662, which is overexpressed in various neoplasms, including breast and prostate, has shown an elevated expression in gallbladder cancer tissues and has been linked to the promotion of aggressive tumor cell traits." (PMID 40141179, 2025).
melanoma (3 papers, 2021 to 2025). A malignant, usually aggressive tumor composed of atypical, neoplastic melanocytes. "High expression of LINC00662 in melanomas was associated with a poor patient prognosis." (PMID 38169586, 2024). "The silencing of LINC00662 in vitro inhibited the proliferation, migration, and invasion of melanoma cells." (PMID 38169586, 2024). "The expression of LINC00662 was markedly higher in the melanoma cells, compared with the HEMa-LP cells." (PMID 38169586, 2024). "Silencing of LINC00662 suppressed the proliferation, migration, and invasion of melanoma cells in vitro and in vivo, while overexpression of LINC00662 promoted melanoma cell proliferation in vitro." (PMID 38169586, 2024). "For example, LINC00662 has been reported to interact with miR-890 in melanomas 18, which does not contradict our results and suggests that the functional mechanisms of LINC00662 are diverse in melanomas and require further investigation." (PMID 38169586, 2024). "Silencing LINC00662 not only inhibited cell proliferation, cell migration, and invasion in vitro, but also inhibited tumor growth in vivo, while LINC00662 overexpression promoted melanoma cell proliferation, suggesting that LINC00662 had an oncogenic effect in melanomas." (PMID 38169586, 2024). "Our findings suggested that the LINC00662/miR-107/ POU3F2 axis may be one of the ways that LINC00662 promotes melanoma growth and metastasis." (PMID 38169586, 2024). "Notably, our study identified POU3F2 as a downstream gene of the LINC00662/miR-107 axis in melanoma." (PMID 38169586, 2024). "Notably, a previous study has shown that miR-107 was a novel tumor suppressor targeting POU3F2 in melanoma 19, and our bioinformatics analysis predicted that miR-107 could be a target of LINC00662." (PMID 38169586, 2024). "Overall, our results confirmed that LINC00662 promoted melanoma progression by sponging miR107 and inducing POU3F2, highlighting the mechanism of the LINC00662/miR-107/POU3F2 axis in melanoma cell proliferation and invasion." (PMID 38169586, 2024). "Therefore, LINC00662 can be regarded as a promising prognostic and therapeutic target for patients with OSCC, melanoma, and AML." (PMID 34354995, 2021).
osteosarcoma (3 papers, 2022 to 2025). A usually aggressive malignant bone-forming mesenchymal neoplasm, predominantly affecting adolescents and young adults. "Because the pathogenesis of osteosarcoma is complex, some other downstream targets of LINC00662 are needed to be explored." (PMID 35123530, 2022).
head and neck squamous cell carcinoma (1 paper, 2024). A squamous cell carcinoma that arises from any of the following anatomic sites: lip and oral cavity, nasal cavity, paranasal sinuses, pharynx, larynx, and salivary glands. "Linc00662 may serve as a novel diagnostic and target marker for head and neck squamous cell carcinoma." (PMID 38911389, 2024).
liver cancer (1 paper, 2022). An epithelial or non-epithelial malignant neoplasm that arises from the liver. "For instance, LINC00662 expedites the proliferation and invasion of liver cancer cells by activating Wnt/β-catenin signaling." (PMID 35037833, 2022).
lung squamous cell carcinoma (1 paper, 2022). "LINC00662 was first reported to be highly expressed in patients with lung squamous cell carcinoma." (PMID 35158906, 2022).